CFAP157 (cilia and flagella associated protein 157)
Description:
Specifically required during spermatogenesis for flagellum morphogenesis and sperm motility. May be required to suppress the formation of supernumerary axonemes and ensure a correct ultrastructure.
Synonyms: C9orf117
Tractability: PROTAC: ubiquitination databases record sites on it.
Gene: Protein-coding gene on chromosome 9 (127,706,988 to 127,716,002, forward strand). Ensembl gene ENSG00000160401.
Subcellular location: Cytoplasm, cytoskeleton, cilium basal body
Subcellular location (Human Protein Atlas): Cytosol; Plasma membrane
Gene Ontology:
Molecular function: microtubule binding
Biological process: sperm axoneme assembly
Cellular component: ciliary basal body; cilium
Genetic constraint (gnomAD): Loss-of-function variants: 44 observed, 56.67 expected, observed/expected ratio (o/e) 0.78, 90% interval 0.61 to 1. The upper end of that interval is the gene's LOEUF score, 1, which puts it in group 4 of 6, group 1 being the genes least tolerant of losing a copy. Missense variants: 606 observed, 653.77 expected, observed/expected ratio (o/e) 0.93, 90% interval 0.87 to 0.99. Synonymous variants: 267 observed, 266.15 expected, observed/expected ratio (o/e) 1, 90% interval 0.91 to 1.11.
Homologues: Orthologues: chimpanzee CFAP157 (99% identical), macaque CFAP157 (96% identical), dog CFAP157 (76% identical), pig CFAP157 (72% identical), guinea pig CFAP157 (70% identical), rabbit CFAP157 (68% identical), rat Cfap157 (66% identical), mouse Cfap157 (65% identical), tropical clawed frog cfap157 (40% identical), zebrafish cfap157 (32% identical), Drosophila melanogaster CG17122 (21% identical).
Diseases named in the same sentence as CFAP157 in open-access papers:
CFAP157 is named in the same sentence as 2 diseases in open-access papers, as found by Europe PMC text mining. Sharing a sentence is not in itself a finding about the gene and the disease.
CFAP157 shares sentences with these, for which no sentence is quoted: infertile (1 paper); Tumor (1).